HES1 (hes family bHLH transcription factor 1)
Diseases named in the same sentence as HES1 in open-access papers (continued):
Sharing a sentence is not in itself a finding about the gene and the disease.
pancreatic cancer (continued). "Moreover, overexpression of Bcl-2 increased Hes1 expression, while siRNA to Bcl-2 reduced Hes1 expression in the pancreatic cancer cells studied." (PMID 22319533, 2012). "In a mouse model of pancreatic cancer, TNFα induces the activation of Ikkβ, a component of the NF-κB signaling, that promotes the expression of Notch target genes HES1 by inducing histone H3 phosphorylation at the HES1 promoter resulting in transcriptional activation." (PMID 30154786, 2018). "Specific inhibitors of HES1, such as JI051 and its derivative JI130, were tested on pancreatic cancer cell lines and in xenograft experiments, showing suppression of cell growth and cell cycle arrest in vitro and a significant decrease in tumor growth in vivo." (PMID 32630477, 2020). "Next, we analyzed the activity of AdNuPARmLuc with respect to AduPARLuc in pancreatic cancer cells and tumorspheres from cells and PDX tumors, expressing NOTCH receptors and the surrogate marker of Notch signaling pathway HES1." (PMID 28186974, 2017). "We also observed similar effects on HES1 transcript levels following co-culture of JAG1-high and -low XPA3 pancreatic cancer cells." (PMID 25557173, 2015). "A gamma secretase inhibitor (GSI) that inhibits the Notch pathway and a shRNA targeting the Notch target gene Hes1 were used to assess the role of the Notch pathway in CSC population maintenance and pancreatic tumor growth." (PMID 24647545, 2014). "In pancreatic cancer cells, pulse of NOTCH1 activation led to increased expression of NOTCH target genes namely HES1 and c-MYC." (PMID 24392017, 2013). "Previous reports indicated that Lnx2 knockdown decreased the expression of the Notch target gene, Hes1, in bon-derived macrophages but did not affect the Notch pathway in a pancreatic cancer cell line." (PMID 36674899, 2023). "A speculative take is that in pancreatic cancer, low concentrations of SOX9 that would ordinarily fail to produce the dimers necessary for driving HES1 expression are overcome by sufficient levels of MYEOV, which acts as a stand-in." (PMID 35451603, 2022). "The expressions of the Notch1/Jagged1/Hes-1 signaling pathway components (Notch1, Jagged1, and Hes1) in PANC-1 and AsPC-1 cells were examined by qRT-PCR and Western blot tests to assess the biological relevance of SNHG7 in pancreatic cancer stemness and Folfirinox resistance." (PMID 34631547, 2021). "Our in vitro results clearly showed that the inhibition of Notch signalling by GSI resulted in a dose-dependent growth attenuation of human pancreatic tumor initiating CD44+/EpCAM+ cells, down regulated the Notch target Hes1 and decreased EMT-related molecules." (PMID 23094026, 2012). "Altogether, these imply that C5EOSEW5050ESA may confer gemcitabine-resistant pancreatic cancer cells to necrotic cell death through the blockade of the Notch signalling pathway by downregulating Notch1 ICD, HES-1, and HEY-2 to potentiate gemcitabine sensitivity in resistant pancreatic cancer cells." (PMID 36685076, 2023). "Moreover, the tumors expressed some well-established markers of human pancreatic cancer, including the ductal markers CK19, mucin 5 (Muc5), matrix metalloproteinase 7 (MMP7), and hairy and enhancer of split 1 (Hes1), the indicator of the active Notch signaling pathway." (PMID 30910991, 2019). "In the present study, we observed Hes1 expression in both cytoplasm and nuclei of malignant and nonmalignant cells and tissues, which is consistent with the previous reports in colorectal cancer, pancreatic cancer, and rhabdomyosarcoma." (PMID 26452025, 2015). "Overexpression of JAG1 also induced HES1, but not HEY1, in the pancreatic cancer cell line XPA3." (PMID 25557173, 2015).
colon carcinoma (27 papers, 2013 to 2024). "Next, we validated the association between the expression of ARID3B and HES1 expression in 130 samples from colon cancer patients." (PMID 32483441, 2020). "As observed by IHC and despite a very low number of samples in each arms, we confirmed a statistically significant association of high expression of HES1 with a decreased risk of death in colon cancer patients, only when their tumor express high RIP140 expression (P = 0.048)." (PMID 38459621, 2024). "Our data identify RIP140 as a key regulator of the Notch/HES1 signaling pathway, with a dual effect on HES1 gene expression at the transcriptional level and a strong impact on colon cancer cell proliferation." (PMID 38459621, 2024). "This regulation of HES1 activity/expression has an impact on colon cancer cell proliferation and CRC prognosis." (PMID 38459621, 2024). "Nonetheless, this work strongly reinforces the role that RIP140 plays in intestinal tumorigenesis by controlling the Notch/HES1 signaling, a major molecular pathway involved in colon cancer." (PMID 38459621, 2024). "It has been reported that STAT3 activity is amplified by HES1 in mouse neuroepithelial cells and colon cancer cells." (PMID 37373457, 2023). "Recent studies revealed that a high HES1 expression level, which was stimulated by aberrant Notch signaling, correlates with increased cell proliferation in pancreatic and colon cancer." (PMID 35136410, 2022). "Honokiol, a traditional Chinese and Japanese herbal therapeutic, inhibited Notch pathway components, including Notch-1 and -2, Jagged-1, Hes-1, and subunits of the gamma secretase complex in melanoma, hepatocellular carcinoma, and colon cancer cells." (PMID 35408894, 2022). "EGCG inhibited Notch-2 in colon cancer cell line, and nearly ablated Hes-1 gene expression in colon cancer cells, suggesting pathway deactivation." (PMID 35408894, 2022). "Microarray analysis showed that Notch1 and Hes1 were increased during the development from physiological healthy colonic mucosa to colon cancer, whereas Notch2, Jag1 and Dll3 remained unchanged." (PMID 32796631, 2020). "To further analyse the effect of miR-142-3p and exosomes from BM-MSCs on Notch signal pathway in human colon cancer, we examined the expression of Numb and Notch target genes: Hes1, P21, and cyclin D3, by real-time PCR." (PMID 30220706, 2018). "Otherwise, Fei Gao demonstrated that EMT was enhanced by HES1, which facilitates colon cancer cell aggressiveness and inhibited by HES1 silencing." (PMID 29665790, 2018). "The tumor stem cell marker CD133 shows a slight positive correlation with the HES1 gene in colon cancer." (PMID 28881812, 2017). "Our previous study showed that hes1 was involved in the self-renewal and tumourigenicity of stem-like cancer cells in colon cancer." (PMID 26452029, 2015). "Transwell and Boyden assays indicated that inhibition of Bmi-1 reduced the migratory/invasive phenotype of Hes1-expressing colon cancer cells, which was confirmed by in vivo experiments." (PMID 26452029, 2015). "Here, we demonstrated that depleting Hes1 in colon cancer cells didn’t affect the cell proliferation but increased beta-galactosidase expression, indicating that Hes1 depletion induces colon cancer cell senescence." (PMID 26650241, 2015). "We did not observe increased invasion ability in HCT116 and HT29 cells expressing mutant Hes1, suggesting that the DNA binding domain is important for the invasion ability of colon cancer cells." (PMID 26650241, 2015). "Taken together, our results suggest that upregulation of Hes1 is sufficient to induce EMT and enhance invasiveness of colon cancer cells in vitro, moreover, Hes1 induces cytoskeleton reconstruction of colon cancer cells." (PMID 26452029, 2015). "Our recent study also demonstrated that Hes1 was essential for the self-renewal and tumourigenicity of stem-like cancer cells in colon cancer." (PMID 26452025, 2015).
colon carcinoma (continued). "Caspase 9 was upregulated in Hes1 inhibited colon cancer cells, whereas down-regulated in Hes1 over-expressed cells." (PMID 26452029, 2015). "Taken together, our results indicate that Hes1 plays a quantitative role in the development and progression of colon cancer and suggest a mechanism that links Hes1 to Bmi-1/PTEN/Akt/GSK3β pathway." (PMID 26452029, 2015). "By silencing Bmi-1 with RNAi in Hes1-expressing cells, we found that Bmi-1-silencing abrogated Hes1 protection of colon cancer cells from apoptosis, reduced the accelerated cell growth and Akt activation induced by Hes1." (PMID 26452029, 2015). "In contrast, p-Akt1 expression in Hes1-expressed colon cancer cells was observed to increase significantly in comparison with that in the control cells." (PMID 26452029, 2015). "In this study, we found that Hes1 promoted EMT and enhanced the invasiveness of colon cancer cells, while silencing Hes1 repressed the EMT phenotype and reduced transformation and metastatic potential of colon cancer cells in vitro and in vivo." (PMID 26452029, 2015). "To explore the roles of Hes1 in colon cancer cells, we examined Hes1 expression levels in 6 colon cancer cell lines using quantitative RT-PCR and found high Hes1 expression levels in CaCo2 and SW48 cells and low Hes1 expression levels in HCT116 cells." (PMID 26650241, 2015). "In Veenendaal’s study, they observed higher Hes1 expression in primary colon cancers but lost expression in regional and distant metastases." (PMID 26650241, 2015). "As several matrix metalloproteinases (MMPs) mediate invasion of cancer cells, we studied the expression of a panel of MMPs in colon cancer cells upon Hes1 knockdown." (PMID 26650241, 2015). "Our findings suggest that HES1 regulate MMP14 expression through up-regulating STAT3 activity in colon cancer cells." (PMID 26650241, 2015). "Together, these results demonstrate that Bmi-1 is important in mediating the cell growth promotion, Akt activation and antiapoptotic function of Hes1 in colon cancer cells." (PMID 26452029, 2015). "In this study, we found that Bmi-1 was up-regulated in colon cancer tissues and expressed positively correlated with the expression of Hes1." (PMID 26452029, 2015). "Hence, the elucidation of the underlying signalling network that regulates these Hes1-associated changes of biological behavior, for example, enhanced metastatic potential and cancer stem cell features, will provide important insights into the exact role of Hes1 in colon cancer." (PMID 26452029, 2015). "Results showed that Hes1 and Bmi-1 were upregulated in the colon cancer tissue compared with the normal samples." (PMID 26452029, 2015). "Results of MTT assay displayed that Hes1 promoted cell growth in SW620 and HCT116 cells, whereas Hes1 shRNA inhibited cell growth in colon cancer cells (P < 0.05 or 0.01)." (PMID 26452029, 2015). "Hes1 plays a role in the initiation of colon cancer and is involved in the self-renewal and tumourigenicity of stem-like cancer cells in colon cancer." (PMID 26452029, 2015). "Results of Microarray demonstrated an increased expression of Hes1 in colon cancer biopsy samples compared with control normal samples, which was confirmed by qPCR shown in the latter part of the article." (PMID 26452029, 2015). "Herein, we demonstrate that overexpression of Hes1 suppresses cell apoptosis, promotes cell growth, migration in colon cancer cells." (PMID 26452029, 2015). "Immunohistochemistry on a colon cancer tissue microarray confirmed that Hes1 is overexpressed in primary colon cancer tissues." (PMID 25309874, 2014). "To disclose the possible convergent points and to clarify the potential mechanism by which LEF1 regulates proliferation and tumorigenesis, we detected the expression of Notch intracellular domain (NICD)/RBP-jκ/Hes1 pathway genes in these colon cancer cells." (PMID 24098538, 2013).
colon carcinoma (continued). "For instance, a previous study concluded that colon cancer cells with DDR1 overexpression have the ability to survive more due to the activation of Notch1 which stimulates the expression of pro-survival genes Hes1 and Hey2." (PMID 37271822, 2023). "For example, HES1 expression oscillates with a period of around 5 h in human colon cancer cells." (PMID 36377847, 2022). "However, a GSI DAPT or Notch1 knockdown improved radiation sensitivity of colon cancer cells directly by affecting the Notch1/HES1 axis, leading to enhanced irradiation-induced DNA damage and attenuated radiation-triggered DNA-PK activity." (PMID 34680255, 2021). "Conversely, a few studies have reported decreased Hes-1 levels in colon carcinomas compared with adenomas, indicating that the involvement of Notch-1 signaling in the initiation and development of CRC remains unclear and controversial." (PMID 30323897, 2018). "This study demonstrated up-regulated active Rac1, CDC42 and RhoA expression in Hes1-expressing colon cancer cells, whereas down-regulated active Rac1, CDC42 and RhoA expression in Hes1-silencing cells, which indicated that Hes1 induced cytoskeleton reconstruction of colon cancer cells." (PMID 26452029, 2015). "We therefore evaluated whether STAT3 activity plays a role in HES1’s regulation of MMP14 in colon cancer cells." (PMID 26650241, 2015). "However, a decreased p-Akt1 expression was observed in Hes1-inhibited colon cancer cells in comparison with that in the control cells." (PMID 26452029, 2015). "Thus, we investigated effects of Hes1 on cell invasion and motility in colon cancer cells by conducting assays for Transwell chamber and Matrigel-coated Boyden chamber invasion and wound healing." (PMID 26452029, 2015). "In addition, PTEN reduced the invasive phenotype and cytoskeleton reorganization of Hes1-expressing colon cancer cells and restored the Hes1-induced EMT phenomenon in cancer cells." (PMID 26452029, 2015). "In addition, Hes1 acts as a marker of normal colon stem cells, however, an increase in Notch signalling, including the Notch target Hes1, may contribute to the initiation of colon cancer." (PMID 26452029, 2015). "Thus, we conclude that Hes1 might play an important role in the tumourigenesis, metastasis and development of colon cancer." (PMID 26452029, 2015). "To determine whether any correlation exists between Hes1 expression and the expression of Bmi-1 in colon cancer biopsy samples, we obtained RNA from 28 normal samples and 28 colon cancer samples and analysed the expression levels of Hes1 and Bmi-1 through qRT-PCR." (PMID 26452029, 2015). "Several target genes induced by HES1 in CRC cells have been identified including the oncogene BMI1, which promotes invasion and migration of colon cancer cells." (PMID 38459621, 2024). "mRNA expression levels of NOTCH-1, NOTCH-3, NOTCH-4, JAG-1, DLL-4, Hes-1, and Hey-1 were quantified to elucidate the action of endostatin/CTX on the notch signaling pathway in colon cancer." (PMID 26762567, 2016). "Herein, we found that Hes1 promoted cell growth in SW620 and HCT116 cells, whereas Hes1-silencing inhibited cell growth in colon cancer cells." (PMID 26452029, 2015). "In the current study, we found that Hes1 suppressed cell apoptosis, promoted cell growth, induced EMT phenotype and cytoskeleton reconstruction, and enhanced the metastatic potential of colon cancer cells in vitro and in vivo." (PMID 26452029, 2015). "It was reported that Hes1 activates signal transducers and activators of the transcription 3 (STAT3) pathway, and that STAT3 controls MMP1 expression in colon cancer cells." (PMID 26650241, 2015). "Our results provide functional and mechanistic links between Hes1 and Bmi-1/PTEN/Akt/GSK3β signaling in the development and progression of colon cancer." (PMID 26452029, 2015). "Here, results indicated that Hes1 downregulated PTEN, and promoted Akt activation and GSK3β phosphorylation in colon cancer cells." (PMID 26452029, 2015).
colon carcinoma (continued). "In addition, some studies have found that the activation of Notch1/Hes1 signaling pathway, as a downstream pathway of SIRT1, can induce apoptosis in esophageal squamous cell carcinoma and colon cancer cells, as well as inhibit their lymph node metastasis." (PMID 38828455, 2024). "Analysis of colon cancer cells individually overexpressing each of the four isoforms revealed an increased basal Notch signaling in NUMB2 and -4, as shown by the expression of the ‘universal’ targets HES1 and HEY1." (PMID 36346211, 2022). "The absence of HES1 has been shown to weaken the tumorigenic capacity of oral squamous cell carcinoma cells, as well as colon cancer and pancreatic cancer cells." (PMID 29665790, 2018). "We then stably expressed HES1 or a mutant Hes1 lacking the DNA-binding domain, in HCT116 and HT29 colon cancer cells." (PMID 26650241, 2015).